HOXB13 (homeobox B13)
Diseases named in the same sentence as HOXB13 in open-access papers (continued):
Sharing a sentence is not in itself a finding about the gene and the disease.
breast carcinoma (continued). "To conclude, none of the recurrent HOXB13 mutations that we identified in the Dutch population were associated with breast cancer risk, although it may be worthwhile to evaluate p.R217C in a larger study or a population with a higher allele frequency." (PMID 27424772, 2016). "Previously, it was shown that a simple homeobox B13:interleukin 17 receptor B two-gene ratio (hereafter referred to as HOXB13:IL17BR) could predict recurrence in a sample of patients with estrogen receptor (ER)-positive breast cancer receiving adjuvant tamoxifen therapy." (PMID 23497539, 2013). "The 10-year absolute risks of breast cancer death for ER-positive, tamoxifen-treated patients were 3.7% (95% CI 1.9% to 5.4%), 5.9% (95% CI 3.0% to 8.6%), and 12.9% (95% CI 7.9% to 17.6%) for those in the low-, intermediate- and high-risk groups, respectively, when classified by MGI+HOXB13:IL17BR." (PMID 23497539, 2013). "Distinct cancers rely on unique regulatory circuits: for instance, HCC frequently engages SIRT1–p62 or PCAF–microtubule pathways, whereas breast cancer emphasizes p300/CREBBP-driven stabilization of transcription factors (e.g., HOXB13, RB1CC1)." (PMID 41213956, 2025). "HBXIP promotes K277 acetylation of homeobox B13 (HOXB13, a transcription factor) and prevents its degradation by CMA, which eventually leads to drug resistance in breast cancer." (PMID 40083922, 2025). "A recent study revealed frequent copy number gain or amplification of HOXB13, including co-amplification with ERBB2, as a mechanism driving increased HOXB13 expression in a subset of breast cancer." (PMID 40137996, 2025). "For instance, hepatitis B virus X-interacting protein (HBXIP) inhibits CMA-mediated homeobox B13 (HOXB13) degradation by enhancing acetylation at Lys 277, leading to the expression of pro-inflammatory cytokine IL-6 and tamoxifen resistance in breast cancer." (PMID 36694209, 2023). "This study compares the performance of the Breast Cancer Index, BCI (HOXB13/IL17BR, H/I), with expression of estrogen (ER), progesterone (PR), and androgen receptors (AR), and Ki67, for prediction of EET benefit." (PMID 36527133, 2022). "A previous study had reported that some homeobox genes, such as HOXB13, TLX1, and HNF1B, were hypermethylated in the early stages of breast cancer." (PMID 32156290, 2020). "In a previous study, we have sequenced the entire coding region of HOXB13 in 1,250 familial non-BRCA1/2 breast cancer cases and 800 controls." (PMID 32546843, 2020). "Our study highlights that HBXIP enhances HOXB13 acetylation to prevent HOXB13 degradation and co-activates HOXB13 in the promotion of TAM resistance of breast cancer." (PMID 29471853, 2018). "Studies have shown that a two-gene ratio (HOXB13:IL17BR) and a five-gene (BUB1B, CENPA, NEK2, RACGAP1, RRM2) molecular grade index (MGI) are predictive of clinical outcomes among early-stage breast cancer patients." (PMID 23497539, 2013). "A 5-gene assay was also developed quantifying the expression of CHDH, HOXB13, IL17BR, MIB1 and MKI67 to identify a subgroup of early stage estrogen receptor–positive breast cancer patients with very poor outcome despite endocrine therapy." (PMID 23468873, 2013). "Breast Cancer Index (BCI) combines two independent biomarkers, HOXB13:IL17BR (H:I) and the 5-gene molecular grade index (MGI), that assess estrogen-mediated signalling and tumor grade, respectively." (PMID 21999244, 2011). "HOXB13, HOXA10 and HOXA1 genes are hyper-methylated in breast cancer patients." (PMID 33225883, 2020). "In ER-positive patients treated with tamoxifen, the risk for breast cancer death was positively associated with HOXB13:IL17BR, MGI, MGI+HOXB13:IL17BR, and BCI in models without tumor size and tumor grade." (PMID 23497539, 2013). "Among ER-positive, lymph node-negative patients not treated with adjuvant chemotherapy, MGI+HOXB13:IL17BR and BCI were associated with risk of breast cancer death." (PMID 23497539, 2013).
breast carcinoma (continued). "In an independent population of lymph node-negative breast cancer patients from a community hospital setting, we evaluated the performance of two risk classifiers that have been derived from these gene signatures combined, MGI+HOXB13:IL17BR and the Breast Cancer Index (BCI)." (PMID 23497539, 2013). "Our previous study of the HOXB13:IL17BR expression ratio indicated that the two genes individually could function as separate prognostic and treatment predictive markers in breast cancer." (PMID 20649975, 2010). "For all of the endocrine-untreated patients, irrespective of ER status, neither the rate of distant recurrence nor the breast cancer-related survival differed between patients with different levels of HOXB13 protein expression in the tumor." (PMID 20649975, 2010). "It is believed that the expression pattern and role of HOXB13 can be significantly different in breast cancers and PCa based on the following observations: 1) Breast tissues are HOXB13-negative as reported by many groups." (PMID 20504375, 2010). "In an independent population of lymph node-negative invasive breast cancer patients who did not receive adjuvant chemotherapy, we demonstrate that MGI+HOXB13:IL17BR and BCI are associated with risk of breast cancer death among ER-positive patients treated and untreated with tamoxifen." (PMID 23497539, 2013). "No studies have been made regarding the HOXB13 protein levels in breast cancer." (PMID 20649975, 2010). "Accordingly, all cultured breast cancer cells, including several MCF7, MCF10a, T47D, and MDA 231, showed no expression or only minimally expressed HOXB13." (PMID 20504375, 2010). "We have shown that HOXB13 is predictive of response to adjuvant tamoxifen therapy, in terms of a longer DRFS and BCS for tamoxifen-treated breast cancer patients if the protein expression is low or absent." (PMID 20649975, 2010).
prostate tumors (23 papers, 2005 to 2025). "PERTINENT FINDINGS: Prostate tumor SUVs of PyL and 18F-rhPSMA-7.3 were significantly associated with HOXB13 expression as assessed by mRNA analysis or by immunohistochemical staining." (PMID 38936974, 2024). "Although somatic mutations to FOXA1 and inherited mutations to HOXB13 are potential drivers, studies of prostate tumors suggest mostly that differential activity of these factors is associated with disease progression." (PMID 36181613, 2022). "Despite efforts devoted to elucidating the impact of HOXB13 mutations, investigation on clinical prostate tumor tissues shows that HOXB13 gene expression at both mRNA and protein levels does not differ between samples carrying the variant and wild-type allele." (PMID 31013831, 2019). "This study has provided important insights into the effect the HOXB13 variant has on gene transcription in prostate tumour tissue but there are some limitations in the interpretation of data." (PMID 29259341, 2017). "FASN expression is also significantly increased in prostate tumors from carriers of the germline HOXB13 G84E mutation compared with matched controls, consistent with a report that HOXB13 may contribute to epigenetic regulation of FASN in vitro." (PMID 38112617, 2024). "Therefore, the role of HOXB13 in prostate tumour development remains unclear and the mechanism by which the HOXB13 gene and, specifically, the G84E variant promotes prostate carcinogenesis, is largely unknown." (PMID 29259341, 2017). "Accordingly, treatment with CCS1477 effectively abolished HOXB13-KD-induced lipid accumulation, and thus PCa cell invasion in vitro and prostate tumor metastasis in vivo." (PMID 41277556, 2025). "In non-transformed prostate cell line, FOXA1, when co-expressed with HOXB13, reprograms genome-wide AR occupancy to an aggressive prostate tumour model." (PMID 39796635, 2024). "In line with this, a set of reprogrammed AR‐binding regions characterized by FOXA1 and HOXB13 colocalization is acquired in prostate tumors." (PMID 32333502, 2020). "Though this is the largest and most comprehensive study of prostate tumors arising in HOXB13 G84E carriers, and the only study with matched controls, this work has some limitations that bear discussion." (PMID 28186998, 2017). "This study demonstrated that HOXB13 was overexpressed in androgen-refractory prostate tumors and was involved in providing a positive growth signal to PCa cells in the absence of androgen." (PMID 20504375, 2010). "In this report, we have demonstrated that HOXB13 was also overexpressed in hormone-refractory prostate tumors; its expression provided a positive growth signal in the absence of androgen." (PMID 20504375, 2010). "Though prostate tumors from HOXB13 G84E carriers are frequently low grade and indolent, these results may have therapeutic implications for the rare carriers who develop metastatic disease and who may benefit from FASN inhibitors." (PMID 38112617, 2024). "Studies have shown HOXB13-mediated repression of Androgen Receptor (AR) signaling, suggesting that HOXB13 may function as a growth suppressor in prostate tumors." (PMID 32012197, 2020). "Most PrCa HOXB13 mutations (including the original G84E mutation) are located within the MEIS-interacting domain, emphasizing the importance of MEIS/HOX interactions in prostate tumor biology." (PMID 32553107, 2020). "To identify HOXB13 transcriptional targets in metastatic PCs, we performed integrative bioinformatics analysis of differentially expressed genes (DEGs) in the proximity of the human prostate tumor-specific AR binding sites." (PMID 31273254, 2019). "However, given the infrequency of HOXB13 loss in prostate tumor specimens, this scenario is not expected to be observed clinically." (PMID 32553107, 2020).
prostate tumors (continued). "We observed that following HOXB13 reduction, genes which are highly expressed in C4-2B/pHOXB13KO were downregulated in human prostate tumors while those with reduced expression in C4-2B/pHOXB13KO were upregulated in human prostate tumors compared to normal prostates." (PMID 31273254, 2019). "Fourteen of the 47 prostate tumor-specific ARBSs were co-occupied by both FOXA1 and HOXB13, implying that FOXA1 and HOXB13 also contribute to the regulation of these DEGs in PCa." (PMID 40525903, 2025). "Of the 13 prostate tumor-specific ARBSs, five were co-occupied by both FOXA1 and HOXB13, suggesting that FOXA1 and HOXB13 also contribute to the regulation of our DE-lncRNAs in PCa." (PMID 37140987, 2023). "In a cohort of 177 laser-capture microdissected foci of prostate tumors, KMT2A expression was positively correlated with MYC activity, AR activity, and HOXB13 expression, but decreased with tumor grade severity." (PMID 36181613, 2022). "We observe that each Gleason pattern 4 tumour is enriched for FOXA1, HOXB13 and CDX2 binding motifs, suggesting that higher-grade prostate tumours converge on the same trans-regulatory landscape." (PMID 34911933, 2021). "Our results, combined with the analysis of the TCGA data set, show that prostate tumours with Gleason pattern 4 share a common transcriptional regulatory programme defined by an enrichment of FOXA1, HOXB13 and CDX2 binding sites." (PMID 34911933, 2021). "We anticipate that there is a similar synergy between FOXA1, HOXB13 and CDX2 TFs in remodelling the chromatin structure in high-grade prostate tumours." (PMID 34911933, 2021). "In summary, our analysis of MYC-expressing prostate tumors demonstrates an inverse relationship with MEIS1 expression, which in turn is negatively correlated with HOXB13 expression and AR activity." (PMID 32681068, 2020). "Several transcription factors, including NKX3-1, HOXB13, HOXC6, HOXD11 and HOXD13, were also found to have deregulated expression in the stromal reaction to invasive prostate tumors." (PMID 21611158, 2011). "Deregulation of CRT by HOXB13 results from the downregulation of TCF4 transcription factors, although aberrant activation of CRT pathway is seen in only small fractions of prostate tumours." (PMID 15928669, 2005). "We found low-grade prostate tumours were significantly enriched for the AP-1 family of TF binding sites (JUN, JUNB, JUND and FOS, FOSB and FRA1, and the closely related activating TFs: ATF and CREB), in contrast to high-grade prostate tumours that were enriched for FOXA1, HOXB13 and CDX2." (PMID 34911933, 2021). "In parallel to our observations, we found FOXA1, HOXB13 and CDX2 to be highly enriched in prostate tumours with primary Gleason pattern 4 (Gleason score 4 + 4 and 4 + 5 patients) as compared to tumours that are predominantly Gleason pattern 3 (Gleason score 3 + 4)." (PMID 34911933, 2021). "Notably, genes associated with luminal differentiation (i.e. FOXA1, TMPRSS2, HOXB13, KLK3, KLK2) had significantly reduced expression in the ‘low’ NKX3.1 prostate tumors." (PMID 30266798, 2018). "To date, the molecular features of prostate tumors occurring in HOXB13 G84E carriers have not been studied in a large cohort of patients." (PMID 28186998, 2017). "In this study we did not observe significant differences in HOXB13 expression between prostate tumors and NPTs, neither among prostate tumors from different molecular subtypes defined by ETS fusion genes." (PMID 28050579, 2016). "Some studies suggest overexpression of HOXB13 in prostate tumors, while others reported no such change." (PMID 20504375, 2010). "Pioneer transcription factors, including FOXA1, HOXB13, and GATA2, as well as the transcription factor ERG, have prominent roles to play in earlier, hormone-sensitive stages of the disease and in CRPC where AR signaling remains a mainstay of prostate tumor growth." (PMID 36212399, 2022).
colorectal cancer (14 papers, 2005 to 2023). A primary or metastatic malignant neoplasm that affects the colon or rectum. "It has also been suggested to increase the risk for colorectal cancer, with a significant association between the HOXB13 variant and colorectal cancer (OR 2.8)." (PMID 34711244, 2021). "Further, the HOXB13G84E mutation is associated with an increased odds ratio (OR) for colorectal cancer (OR: 2.8, p=0.02), bladder cancer (OR: 1.99, p=0.06), and leukemia (OR: 3.17, p=0.01), further demonstrating the importance of the need to understand how HOXB13 mutations promote cancer." (PMID 32553107, 2020). "While appraising the association between HOXB13-pGly84Glu mutation and colorectal cancer (CRC) patients in two different population registries, 0.48% of the cases had HOXB13 mutation when compared to the control group (0.17%)." (PMID 34617205, 2022). "HOXB13 has a tumor-suppressive function in colorectal cancer, renal cell carcinoma and malignant melanoma." (PMID 25944620, 2015). "Functionally, forced expression of HOXB13 drove colorectal cancer (CRC) cells into growth suppression." (PMID 15928669, 2005). "Similarly, in colorectal cancer, HOXB13 downregulated the protein expression of TCF4, thereby hindering the cell growth." (PMID 33479226, 2021). "Also, HOXB13 was shown to play a part in growth arrest in AR− prostate, colorectal cancer and renal cell carcinoma." (PMID 22808286, 2012). "One study has shown that HOXB13 as a direct DNMT3B target is aberrantly methylated at an upstream CpG island, and functions’ tumor suppressor properties in colorectal cancer cells." (PMID 30105866, 2018). "Suppression or down-regulation of HOXB13 has been observed in other tumors, including colorectal cancer and skin tumors, although the level of HOXB13 protein was not detectable in normal skin." (PMID 20504375, 2010). "In addition, Ghoshal revealed the tumor-suppressive effect of HOXB13 but did not determine the effect of HOXB13 on the anatomical location of colorectal cancer." (PMID 31815008, 2019).
endometrial cancer (13 papers, 2017 to 2025). Primary or metastatic malignant neoplasm involving the endometrium (mucous membrane that lines the endometrial cavity). "CXCL8 secreted from tumor associated macrophage via HOXB13 promoted endometrial cancer cells invasion." (PMID 36532015, 2022). "CXCL8 secreted by tumor associated macrophages (TAM) inhibits ER + expression in endometrial carcinoma (EC) cells through HOXB13, which may be related to invasion, metastasis, and poor prognosis of cancer." (PMID 34384424, 2021). "FTO functions by demethylating m6A modifications of HOXB13 mRNA, thereby promoting metastasis of endometrial cancer through activation of the WNT signaling pathway." (PMID 38200441, 2024). "Indeed, within the realm of endometrial cancer, a noteworthy observation emerges: the expression levels of HOXB13 exhibit an elevation within metastatic tumors." (PMID 38068717, 2023). "Ovarian, cervical and endometrial cancers overexpress HOXB13." (PMID 34983599, 2022). "HOXB13 is also expressed in other carcinomas including endometrial cancer, which in itself does not limit its diagnostic value, but also in pancreatic cancer and hepatocellular carcinoma." (PMID 28555048, 2017). "In an article related to endometrial cancer, the relationship between FTO, HOXB13, and the m6A mechanism was studied." (PMID 38068717, 2023). "FTO alpha-ketoglutarate dependent dioxygenase (FTO) can regulate the mRNA level of homeobox B13 (HOXB13) and promote the metastasis of endometrial cancer via modulating the WNT signaling pathway." (PMID 35156522, 2022). "This interplay between HOXB13, FTO, and the Wnt signaling pathway adds a new layer of complexity to our understanding of endometrial cancer progression, illuminating potential targets for therapeutic intervention and presenting a fascinating area for further investigation." (PMID 38068717, 2023).